CNR1 (cannabinoid receptor 1)
Description:
G protein-coupled receptor for endogenous cannabinoids (eCBs), including N-arachidonoylethanolamide (also called anandamide or AEA) and 2-arachidonoylglycerol (2-AG), as well as phytocannabinoids, such as delta(9)-tetrahydrocannabinol (THC). Mediates many cannabinoid-induced effects, acting, among others, on food intake, memory loss, gastrointestinal motility, catalepsy, ambulatory activity, anxiety, chronic pain. Signaling typically involves reduction in cyclic AMP. In the hypothalamus, may have a dual effect on mitochondrial respiration depending upon the agonist dose and possibly upon the cell type. Increases respiration at low doses, while decreases respiration at high doses. At high doses, CNR1 signal transduction involves G protein alpha-i protein activation and subsequent inhibition of mitochondrial soluble adenylate cyclase, decrease in cyclic AMP concentration, inhibition of protein kinase A (PKA)-dependent phosphorylation of specific subunits of the mitochondrial electron transport system, including NDUFS2. In the hypothalamus, inhibits leptin-induced reactive oxygen species (ROS) formation and mediates cannabinoid-induced increase in SREBF1 and FASN gene expression. In response to cannabinoids, drives the release of orexigenic beta-endorphin, but not that of melanocyte-stimulating hormone alpha/alpha-MSH, from hypothalamic POMC neurons, hence promoting food intake. In the hippocampus, regulates cellular respiration and energy production in response to cannabinoids. Involved in cannabinoid-dependent depolarization-induced suppression of inhibition (DSI), a process in which depolarization of CA1 postsynaptic pyramidal neurons mobilizes eCBs, which retrogradely activate presynaptic CB1 receptors, transiently decreasing GABAergic inhibitory neurotransmission. Also reduces excitatory synaptic transmission (By similarity). In superior cervical ganglions and cerebral vascular smooth muscle cells, inhibits voltage-gated Ca(2+) channels in a constitutive, as well as agonist-dependent manner. In cerebral vascular smooth muscle cells, cannabinoid-induced inhibition of voltage-gated Ca(2+) channels leads to vasodilation and decreased vascular tone (By similarity). Induces leptin production in adipocytes and reduces LRP2-mediated leptin clearance in the kidney, hence participating in hyperleptinemia. In adipose tissue, CNR1 signaling leads to increased expression of SREBF1, ACACA and FASN genes (By similarity). In the liver, activation by endocannabinoids leads to increased de novo lipogenesis and reduced fatty acid catabolism, associated with increased expression of SREBF1/SREBP-1, GCK, ACACA, ACACB and FASN genes. May also affect de novo cholesterol synthesis and HDL-cholesteryl ether uptake. Peripherally modulates energy metabolism (By similarity). In high carbohydrate diet-induced obesity, may decrease the expression of mitochondrial dihydrolipoyl dehydrogenase/DLD in striated muscles, as well as that of selected glucose/ pyruvate metabolic enzymes, hence affecting energy expenditure through mitochondrial metabolism (By similarity). In response to cannabinoid anandamide, elicits a pro-inflammatory response in macrophages, which involves NLRP3 inflammasome activation and IL1B and IL18 secretion (By similarity). In macrophages infiltrating pancreatic islets, this process may participate in the progression of type-2 diabetes and associated loss of pancreatic beta-cells. [Isoform 1]: Binds both 2-arachidonoylglycerol (2-AG) and anandamide. [Isoform 2]: Only binds 2-arachidonoylglycerol (2-AG) with high affinity. Contrary to its effect on isoform 1, 2-AG behaves as an inverse agonist on isoform 2 in assays measuring GTP binding to membranes. [Isoform 3]: Only binds 2-arachidonoylglycerol (2-AG) with high affinity. Contrary to its effect on isoform 1, 2-AG behaves as an inverse agonist on isoform 3 in assays measuring GTP binding to membranes.
Synonyms: CB-R; CB1; CNR; CB1K5; CANN6; CB1A; CB1R
Tractability: Small molecule: an approved drug acts on it; a structure with a bound ligand is known; a high-quality ligand is known; it belongs to a druggable protein family. Antibody: a drug acting on it is in phase 2 or 3 trials; UniProt places it where antibodies can reach, with high confidence; its Gene Ontology location is reachable by antibodies, with high confidence; UniProt predicts a signal peptide or a membrane-spanning region; the Human Protein Atlas places it where antibodies can reach. PROTAC: its protein half-life has been measured; a small molecule that binds it is known.
Target class: Cannabinoid receptor; Family A G protein-coupled receptor; Membrane receptor; Small molecule receptor (family A GPCR); Lipid-like ligand receptor (family A GPCR)
Chemical probes: AM251 (high quality), AM281, MRL-650 (high quality), ibipinabant
Safety:
Unwanted effects reported when the protein is acted on. In parentheses: how it was acted on, where the effect was seen, and who reports it.
dysphoria (Bowes et al. (2012): activation, central nervous system; Lynch et al. (2017): activation, acute dosing, nervous system, cardiovascular)
analgesia (activation; central nervous system; source: Bowes et al. (2012))
anxiety (activation; central nervous system; source: Bowes et al. (2012))
catalepsy (activation, acute dosing; nervous system, cardiovascular; source: Lynch et al. (2017))
decreased blood pressure (activation, acute dosing; nervous system, cardiovascular; source: Lynch et al. (2017))
decreased body temperature (activation, acute dosing; nervous system, cardiovascular; source: Lynch et al. (2017))
decreased convulsions (activation, acute dosing; nervous system, cardiovascular; source: Lynch et al. (2017))
decreased eating (inhibition, acute dosing; nervous system, cardiovascular; source: Lynch et al. (2017))
decreased heart rate (activation, acute dosing; nervous system, cardiovascular; source: Lynch et al. (2017))
decreased locomotor activity (activation, acute dosing; nervous system, cardiovascular; source: Lynch et al. (2017))
decreased pain (activation, acute dosing; nervous system, cardiovascular; source: Lynch et al. (2017))
depression (inhibition; central nervous system; source: Bowes et al. (2012))
dizziness (activation, acute dosing; nervous system, cardiovascular; source: Lynch et al. (2017))
drowsiness (activation, acute dosing; nervous system, cardiovascular; source: Lynch et al. (2017))
drug abuse/dependence (activation, acute dosing; nervous system, cardiovascular; source: Lynch et al. (2017))
emesis (inhibition; central nervous system; source: Bowes et al. (2012))
euphoria (activation; central nervous system; source: Bowes et al. (2012))
hallucinations (activation, acute dosing; nervous system, cardiovascular; source: Lynch et al. (2017))
headache (activation, acute dosing; nervous system, cardiovascular; source: Lynch et al. (2017))
hypothermia (activation; central nervous system; source: Bowes et al. (2012))
increased convulsions (inhibition, acute dosing; nervous system, cardiovascular; source: Lynch et al. (2017))
increased eating (activation, acute dosing; nervous system, cardiovascular; source: Lynch et al. (2017))
increased weight loss (inhibition; central nervous system; source: Bowes et al. (2012))
memory impairment (activation; central nervous system; source: Bowes et al. (2012))
nervousness (activation, acute dosing; nervous system, cardiovascular; source: Lynch et al. (2017))
poor concentration (activation; central nervous system; source: Bowes et al. (2012))
opioid dependence (source: ClinPGx)
weight gain (source: ClinPGx)
Gene: Protein-coding gene on chromosome 6 (88,139,863 to 88,167,364, reverse strand). Ensembl gene ENSG00000118432.
Subcellular location: Cell membrane; Membrane raft; Mitochondrion outer membrane; Cell projection, axon; Presynapse
Subcellular location (Human Protein Atlas): Plasma membrane; Actin filaments
Pathways (Reactome):
Signal Transduction: Class A/1 (Rhodopsin-like receptors); G alpha (i) signalling events
Gene Ontology:
Molecular function: cannabinoid receptor activity; identical protein binding; protein binding; G protein-coupled receptor activity
Biological process: adenylate cyclase-modulating G protein-coupled receptor signaling pathway; cannabinoid signaling pathway; adenylate cyclase-activating G protein-coupled receptor signaling pathway; G protein-coupled receptor signaling pathway, coupled to cyclic nucleotide second messenger; G protein-coupled receptor signaling pathway; regulation of presynaptic cytosolic calcium ion concentration; retrograde trans-synaptic signaling by endocannabinoid
Cellular component: membrane raft; plasma membrane; cytoplasm; presynapse; axon; GABA-ergic synapse; glutamatergic synapse; growth cone; membrane; mitochondrial outer membrane; mitochondrion; presynaptic membrane
Genetic constraint (gnomAD): Loss-of-function variants: 10 observed, 24.44 expected, observed/expected ratio (o/e) 0.41, 90% interval 0.25 to 0.69. The upper end of that interval is the gene's LOEUF score, 0.69, which puts it in group 2 of 6, group 1 being the genes least tolerant of losing a copy. Missense variants: 422 observed, 649.89 expected, observed/expected ratio (o/e) 0.65, 90% interval 0.6 to 0.7. Synonymous variants: 271 observed, 268.3 expected, observed/expected ratio (o/e) 1.01, 90% interval 0.91 to 1.12.
Homologues: Orthologues: macaque CNR1 (100% identical), pig CNR1 (98% identical), rat Cnr1 (97% identical), mouse Cnr1 (97% identical), guinea pig CNR1 (97% identical), tropical clawed frog cnr1 (80% identical), zebrafish cnr1 (70% identical). Paralogues in human: CNR2 (32% identical), LPAR1 (20% identical), S1PR4 (19% identical), S1PR1 (19% identical), S1PR3 (19% identical), S1PR5 (19% identical), GPR6 (18% identical), GPR12 (18% identical), S1PR2 (18% identical), LPAR2 (17% identical), GPR3 (17% identical), LPAR3 (17% identical), and 6 more.
Diseases named in the same sentence as CNR1 in open-access papers:
CNR1 is named in the same sentence as 437 diseases in open-access papers, as found by Europe PMC text mining. Sharing a sentence is not in itself a finding about the gene and the disease. The quoted sentences say what the papers report.
Obesity (328 papers, 2008 to 2026). Accumulation of substantial excess body fat. "The current study aimed to assess the prevalence of metabolic phenotypes of obesity and to evaluate their association with markers related to diabesity, adipokines profile, and two single nucleotide polymorphisms of CNR1 gene." (PMID 41745574, 2026). "The inactivation of the EC system through administration of cannabinoid receptor 1 (CB1R) antagonist or CB1R knockout can ameliorate obesity-associated metabolic disorders such as insulin resistance and compensatory hyperinsulinemia and hepatic steatosis." (PMID 42158822, 2026). "The SNP rs1049353 in the CNR1 gene has been associated with obesity, type 2 diabetes mellitus (T2DM), and metabolic syndrome." (PMID 40431452, 2025). "The expression of various genes was also causally associated with the risk of AD, confirming ACE and BIN1 as risk genes for AD, while a genetically predicted anti-obesity drug target gene CNR1 was a protective factor against AD risk." (PMID 40082927, 2025). "In a mouse model of diet-induced obesity, treatment with the Cannabinoid receptor 1 (CB1) antagonist AM251 resulted in weight loss and reduced inflammation." (PMID 40860192, 2025). "Loss-of-function mutations of Pcsk1, Cnr1, and Bbs10 contribute to the development of obesity-associated features including severe early-onset obesity, increased waist circumference and skin-fold thickness, and higher adiposity." (PMID 36284088, 2022). "The BDNF (rs925946), INSIG2 (rs3771942) and CNR1 (rs6454674) variants are well stablished genetic determinants of obesity." (PMID 34683180, 2021). "Considering other epigenetic modifications possibly occurring in the development of obesity, recently a hypothalamic increase in histone acetylation was reported at CNR1 gene promoter and was linked to increased receptor expression." (PMID 33401515, 2021). "An age-based stratification of DNA methylation levels showed a significant reduction of the epigenetic hallmark at CNR1 promoter in younger (<30 years old) humans with obesity, when compared to age-matching controls." (PMID 33401515, 2021). "Genetic studies have identified several polymorphisms at different locations across the CNR1 gene that have been associated with obesity and related phenotypes, such as metabolic syndrome and dyslipidemia." (PMID 33401515, 2021). "The study was conducted on 5750 patients and demonstrated that CNR1 gene variants increases the risk of obesity and modulates the BMI in the European population." (PMID 33530406, 2021). "For example, candidate gene association approaches using larger samples were used to identify significant associations of variants in the CB1 receptor gene (CNR1) with obesity outcomes, which has been a reproducible association." (PMID 34959715, 2021). "Further, adult mice, in which CNR1 gene was deleted in adipocytes, resulted to be protected from diet-induced obesity and associated with metabolic alterations." (PMID 33401515, 2021). "Previous research results indicate that overexpression and dysfunction of CNR1 cause obesity and hepatic steatosis (fatty liver disease) in a diet-induced obesity mouse model." (PMID 33153215, 2020). "In recent studies, nutmeg has displayed high binding activity to the cannabinoid receptor 1 (CB1), which is associated with the obesity pathway." (PMID 32825154, 2020). "Obesity has been linked to higher endocannabinoid plasma and adipose tissue levels, and altered expression of the cannabinoid receptor 1 (CB1R)." (PMID 32824900, 2020). "We assessed only one polymorphism of the CNR1 gene, but there are many others that have been recently implicated with adverse metabolic profiles and obesity characteristics." (PMID 31723535, 2019). "The 3813G allele at the exon 4 of CNR1 is associated with obesity-related phenotypes like waist circumference and subscapular skinfold thickness in adult men." (PMID 32116676, 2019).
Obesity (continued). "The up-expression of Cnr1 in the hypothalamus has been associated with the leptin resistance in obesity." (PMID 28082878, 2016). "Past studies initially suggested that hepatic Cnr1 deficiency alone prevented the HFD-induced development of hepatic steatosis, insulin resistance, and dyslipidemia, whereas extra-hepatic Cnr1 deficiency was required to prevent HFD-induced obesity." (PMID 26082754, 2015). "Although the Cnr1 inverse agonist rimonabant was an effective anti-obesity agent, it was often associated with affective disturbances such as anxiety and depression that made it unsuitable for routine use." (PMID 26082754, 2015). "The current findings are consistent with prior evidence that the CNR1 H3 haplotype was strongly associated with HDL-C levels in individuals with class III obesity." (PMID 22567136, 2012). "Rimonabant, a cannabinoid receptor 1 blocker in the endocannabinoid (EC) system, was indicated in Europe for the treatment of obesity and overweight patients with associated risk factors but withdrawn on Jan, 2009 because of side effects." (PMID 23449551, 2012). "We have previously shown that genetic variability in CNR1 is associated with low HDL dyslipidemia in a multigenerational obesity study cohort of Northern European descent (209 families, median = 10 individuals per pedigree)." (PMID 21209828, 2010). "Furthermore, the results of genetic studies have proven the existence of CNR1 gene variations associated with obesity and/or metabolic syndrome." (PMID 41096816, 2025). "That study suggested that rs6454674, rs1078602, and rs10485171 in the CNR1 gene may be associated with FM, obesity, irritable bowel syndrome, migraine, and post-traumatic stress disorder." (PMID 36360283, 2022). "The T allele created a binding site for arylhydrocarbon receptor translocator, a member of the basic helix–loop–helix/Per–Arnt–Sim protein family.Genetic polymorphisms in the CNR1 gene have been associated with basal metabolic index, obesity and various metabolic parameters." (PMID 35745668, 2022). "No prior associations with sleep phenotypes have been described with CNR1 rs806368, although this variant has been reported to be associated with increased waist-hip ratio, triglycerides, body mass index, and obesity, which are known risk factors for poorer quality sleep." (PMID 34566715, 2021). "Thus, Cnr1-deficient mice are resistant to diet-induced obesity (DIO) while mice treated with CB1 receptor antagonists are leaner, due to a significant reduction in food intake." (PMID 34064024, 2021). "Furthermore, central dysregulation of CNR1 gene expression has been documented in animal models of obesity in different brain areas, implicated in both homeostatic and hedonic aspects of eating." (PMID 33401515, 2021). "Interestingly, a positive correlation to the BMI and body fat was found for the circulating levels of endocannabinoids, whereas obesity was linked to a reduced adipose expression of Cnr1 and FAAH." (PMID 31910153, 2020). "In the past several years, our group and others have provided evidence that obesity is associated with increased eCB tone in the brain and plasma, altered expression of cannabinoid receptor 1 (CB1 mRNA) and increased eCB levels in the adipose tissue, liver, muscle and pancreas." (PMID 32106469, 2020). "We failed to observe any difference between controls and humans with obesity in the overall population, yet age-based stratification of the data clearly showed a significant reduction of the epigenetic hallmark at both CNR1 and OPRM1 promoters in younger (<30 years old) humans with obesity." (PMID 31258545, 2019). "Consistently, Cnr1 (encoding CB1)-KO mice are protected against diet-induced obesity." (PMID 30692526, 2019). "Polymorphism of the cannabinoid receptor 1 gene (CNR1) may be responsible for individual susceptibility to obesity and related conditions." (PMID 25136364, 2014).